KDM4C (lysine demethylase 4C)
Diseases named in the same sentence as KDM4C in open-access papers (continued):
Sharing a sentence is not in itself a finding about the gene and the disease.
cancer (continued). "Concerning histone demethylases, Jumonji C domain KDMs members of family GASC1/KDM4C and JMJD1C/KDM3C demethylating agents of repressive histone marker H3K9 and KDM7B/PHF8 which specifically demethylate H3K27me1/2, play a critical role in ESCC cancer development." (PMID 31739546, 2019). "Altogether, these observations show for the first time that depletion of KDM4C, but not KDM4B, affects the fidelity of mitotic chromosome segregation, therefore suggesting that CIN in cancers lacking KDM4C can result in part from mitotic chromosome missegregation." (PMID 24728997, 2014).
tumor (43 papers, 2012 to 2026). "Firstly, the expression levels of KDM4C mRNA (encoding JMJD2C protein) were detected in 124 CRC tumor specimens." (PMID 31665047, 2019). "Functional studies using CRISPR/Cas9 gene editing, siRNA-mediated silencing, and selective inhibitors such as SD70 have demonstrated that KDM4C suppression reduces tumor cell migration and metastasis in both in vitro and in vivo models." (PMID 41505486, 2026). "Among epigenetic modifiers, histone demethylases like KDM4C (lysine demethylase 4C) play a pivotal role in tumor progression by removing repressive methylation mark at Histone H3K9/H3K36 and altering chromatin structure and gene expression." (PMID 41505486, 2026). "On the other hand, shRNA-mediated knockdown of KDM4C reduced hepatocellular xenograft tumor growth, and KDM4C silencing reduced cell migration and expression of proteins regulating cell motility—ZEB1 and Snail, in vitro." (PMID 40940894, 2025). "Myricetin and its analogue 22S0 effectively inhibit KDM4C activity, with 22S0 demonstrating promising anti-tumor efficacy in zebrafish and mouse xenograft models." (PMID 40259045, 2025). "KDM4C downregulation substantially decreased tumor cell growth in vitro and in vivo in all KDM4C-amplified cell lines and in a non-amplified cell line (HCC1806) with moderate KDM4C expression." (PMID 40457074, 2025). "Deletion of CTSL also eliminated KDM4C-inhibition-induced tumor growth suppression specifically in KDM4C-amplified cell models where CTSL-mediated histone H3 clipping is observed." (PMID 40457074, 2025). "Fixation and staining of surviving tumor cells showed that inhibition of KDM4C significantly enhanced the proportion of tumor cells killed by T cells." (PMID 35121645, 2022). "Of note, KDM4A knockdown or KDM4C knockout in castration-resistant PCa cells also leads to decreased tumor formation." (PMID 35534851, 2022). "A previous study reported that the levels of KDM4C mRNA (encoding JMJD2C protein) were significantly correlated with TNM stage, distant metastasis, OS and tumor recurrence in CRC." (PMID 35429301, 2022). "The KDM4C-specific epigenetic inhibitor SD70 can reshape the tumor state, activate the expression of CXCL10, and enhance the recruitment and activation of CD8+ T cells, ultimately making tumors more responsive to RT and immunotherapy." (PMID 35121645, 2022). "As expected, adding conditioned medium in which KDM4C was inhibited enhanced CD8+ T cell mediated tumor cell lysis." (PMID 35121645, 2022). "KDM4C was shown to promote tumor angiogenesis by transcriptionally activating the HIF1α/VEGFA signaling pathway." (PMID 35633893, 2022). "Analysis of the immune landscape following KDM4C inhibition revealed increased CD8+ T cell tumor infiltration and activation." (PMID 35121645, 2022). "The expression of cytotoxic molecules in tumor CD8+ T cells was significantly upregulated after genetical or pharmacologic inhibition of KDM4C, indicating that KDM4C inhibition promotes the activation of CD8+ T cells." (PMID 35121645, 2022). "KDM4C overexpression is mediated by gene amplification of 9p24 chromosomal region, which contains several candidate tumor genes, including KDM4C." (PMID 34778065, 2021). "Consistent with our in vitro results, KDM4C inhibition effectively hindered tumor growth in xenografts in a concentration-dependent manner." (PMID 33558705, 2021). "Excitingly, recent studies have demonstrated that SD70 is a novel KDM4C inhibitor and revealed its potential in impeding tumor progression in prostate cancer and acute myeloid leukemia." (PMID 33558705, 2021). "Knockdown (KD) of KDM4C suppressed cell proliferation, soft agar colony formation, and androgen receptor (AR) transcriptional activity in PCa cells as well as reduced tumor growth of human PCa cells in zebrafish xenotransplantation assay." (PMID 31766290, 2019).
tumor (continued). "The downregulation of KDM4C which we have found in untreated HepG2 cells is also an important finding since it has diverse targets in oncogenic or tumor suppressor functions." (PMID 30654452, 2019). "We further evaluated whether KDM4C promotes tumor growth using a mouse xenograft model with SAS cells." (PMID 40259045, 2025). "Knockout of CTSL restores the tumour‐suppressive function lost upon KDM4C depletion." (PMID 41261048, 2025). "In contrast, KDM4C exhibited the opposite trend, with lower expression in tumour tissues." (PMID 38390756, 2024). "Importantly, using the xenograft model, we demonstrated that both tumor size and weight of mice injected with KDM4C stable knockdown HCC cells were decreased compared with those of mice injected with control HepG2 cells." (PMID 37117173, 2023). "Flow cytometry analysis of the tumor immune landscape in transplanted tumors revealed that KDM4C inhibition could significantly increase the proportion of CD8+ T cells." (PMID 35121645, 2022). "qRT–PCR analysis confirmed TCGA results and further demonstrated that patients with metastasis had higher KDM4C expression, suggesting that KDM4C may participate in tumor metastasis progression." (PMID 35871166, 2022). "We next evaluated whether KDM4C knockdown affected tumor growth in vivo using the mouse tumor xenograft model." (PMID 33462212, 2021). "Knockdown of KDM4C also reduced the tumor growth of LNCaP C4-2B cells in a zebrafish model." (PMID 31766290, 2019). "KDM4C silencing in HNSCC cells reduced cell migration in vitro, attenuated invasion and metastasis in zebrafish, and impaired xenograft tumor growth in mice." (PMID 40940894, 2025). "This study investigates the role of KDM4C and its interaction with GATA1 in regulating heme metabolism and tumor progression in HNSCC." (PMID 40259045, 2025). "KDM4C knockdown (KDM4C-KD) hindered HNSCC cell migration using in vitro assays, inhibited metastasis through zebrafish xenotransplantation, and suppressed tumor growth in mouse xenograft models." (PMID 40259045, 2025). "Our study addresses this gap by examining how the interaction between KDM4C and GATA1 collaboratively regulates FECH expression, providing new insights into the molecular mechanisms linking heme metabolism to tumor growth and aggressiveness." (PMID 40259045, 2025). "Several molecules that inhibit KDM4C activity, such as JIB-04 and SD70, have been created and demonstrated anti-tumor effects in preclinical studies." (PMID 38623585, 2024). "Our data indicate that KDM4C and GATA1 cooperate to upregulate FECH, the terminal enzyme in heme biosynthesis, enhancing mitochondrial bioenergetics, oxidative phosphorylation, and supporting tumor aggression." (PMID 40259045, 2025). "Genetical or pharmacological inhibition of KDM4C specifically increased CD8+ T cell infiltration; promoted the proliferation, migration and activation of CD8+ T cells; and alleviated CD8+ T cell exhaustion in mouse tumor tissues." (PMID 35121645, 2022).
KDM4C also shares sentences with these, for which no sentence is quoted: medulloblastoma (5 papers); B-cell lymphoma (3); Hodgkins lymphoma (3); MALT lymphoma (3); adenocarcinoma (2); blood neoplasms (2); glioma (2); acute promyelocytic leukemia (1); bipolar disorder (1); cardiovascular disease (1); Cirrhosis (1); depression (1); diabetes (1); diffuse large B-cell lymphoma (1); essential thrombocythemia (1); fatty liver (1); gastric tumor (1); head and neck squamous cell carcinoma (1); head and neck tumors (1); IgA vasculitis (1); intellectual deficiency (1); kidney damage (1); lung adenocarcinoma (1); lung sarcomatoid carcinoma (1); lymphoma (1); metabolic disease (1); metastatic tumors (1); multiple myeloma (1); neurodegenerative disease (1); osteoporosis (1).
A further 12 diseases each share a sentence with KDM4C in 1 paper.